PHLPP1 (PH domain and leucine rich repeat protein phosphatase 1)
Diseases named in the same sentence as PHLPP1 in open-access papers (continued):
Sharing a sentence is not in itself a finding about the gene and the disease.
cancer (continued). "We identified HSP47 as a novel protein that promotes cancer survival by modulating AKT signaling, probably via PHLPP1, in CRC." (PMID 32587773, 2020). "PH domain and Leucine Rich Repeat Protein Phosphatase 1 (PHLPP1), a member of the PHLPP family, directly dephosphorylates and therefore inactivates AKT to inhibit cancer proliferation." (PMID 31624470, 2019). "Expression of miR-3127 and miR-508 is frequently increased in some human cancers suppressing expression of PIPP as well as other PI3K/AKT signalling pathway components including PTEN, INPP4A and PHLPP1/2." (PMID 28082369, 2017). "For example, genes related to significantly enriched GO terms of cell adhesion and apoptosis, included COL4A3, PHLPP1, and TIA1, which were reportedly downregulated in cancer." (PMID 28903418, 2017). "Recent study has verified that β-TrCP ligase mediates PHLPP-1 ubiquitination and degradation controlling the level of PHLPP-1 in cancer cells." (PMID 27019292, 2016). "Down-regulation of PHLPP1 and PHLPP2 proteins has been found in a variety of malignant tumors, including colorectal cancer, prostate cancer, and chronic lymphocytic leukemia (CLL)." (PMID 26245343, 2015). "We show that PHLPP2 has a divergent catalytic site, exhibits no activity in vitro, and that cancer genomics does not support a role for either PHLPP1 or PHLPP2 in cancer." (PMID 40168118, 2025). "PHLPP1 and PHLPP2 have previously been reported as protein phosphatases that specifically inactivate Akt, a pro-growth and survival kinase hyperactivated in many human cancers." (PMID 40168118, 2025). "Given that PMEPA1 may modulate the expression of PHLPP1 via the PY motif, it is hypothesized that inhibition of PMEPA1 may be involved in the crosstalk mechanism and can be beneficial for cancer therapy." (PMID 38173834, 2023). "Since loss of PHLPP activity leads to hyperphosphorylation of Akt, it is not surprising that PHLPP1/2 expression is reduced or lost in many cancers." (PMID 36180910, 2022). "The inverse correlation between BMI‐1 and PHLPP1/PHLPP2 expression was observed in PTEN positive but not PTEN negative cancers." (PMID 31863623, 2020). "However, the same miRNA can be oncogenic by targeting PH domain leucine-rich-repeat protein phosphatases 1 and 2 (PHLPP1 and PHLPP2) in NSCLC, thereby inducing proliferation of the cancer cells." (PMID 30944831, 2019). "The results revealed that the expression of either PHLPP1 or PHLPP2 was significantly decreased in carcinomas relative to adjacent noncancerous epithelial tissues." (PMID 25793736, 2015). "Furthermore, we show that cancer genomics does not support a role for either PHLPP1 or PHLPP2 in cancer." (PMID 40168118, 2025). "Moreover, several other miRNAs affect the PHLPP1 levels in cancer cells while there is no information available on a potential regulation of PHLPP1 at the posttranscriptional level in insulin-resistant conditions." (PMID 29535681, 2018). "Both microautophagy and CMA might also contribute to cancer development; for example, LAMP2A is highly increased in malignant tumors, including GBM, and it is a predictor of poor prognosis, while the downregulation of other CMA proteins, such as PHLPP1, has been found in several tumors." (PMID 41294817, 2025). "According to that both PHLPP1 and PHLPP2 expressions are lost in diverse cancers, but their role in progression of cancers has not been identified." (PMID 31863623, 2020). "The expression levels of PHLPP1 and PHLPP2 were found to be lost or decreased in carcinomas compared with the adjacent noncancerous mucosae, which was certificated by qRT-PCR and immunohistochemical staining." (PMID 25793736, 2015).
infection (3 papers, 2016 to 2023). The state of being infected such as from the introduction of a foreign agent such as serum, vaccine, antigenic substance or organism. "We find that Phlpp1-/- mice have improved survival following infection with Escherichia coli (E. coli), indicating a role of the phosphatase in innate immunity." (PMID 31408005, 2019). "In contrast, the Phlpp1-/- mice had 2-fold lower IL-6 levels at 5 hr post-infection, but these levels were sustained for up to 24 hr, suggestive of improper resolution of inflammation." (PMID 31408005, 2019). "The protein level of cardiac PHLPP-1 in vivo was decreased in sh-PHLPP-1 infected aged hearts compared with that in sh-Con injected hearts after 72 h infection." (PMID 27019292, 2016).
neurodegenerative disease (2 papers, 2025). A disorder of the central nervous system characterized by gradual and progressive loss of neural tissue and neurologic function. "Overall, PHLPP1 plays a key regulatory role in neurons through its interactions with various substrates, and it is associated with diverse neurodegenerative diseases, including Alzheimer’s disease and Huntington’s disease." (PMID 41024062, 2025). "This region of genetic overlap on PHLPP1 represents a potentially novel AD-risk locus that may inform future research on the shared causal relationship between cerebrovascular health, neurodegenerative disease, and genetic ancestry." (PMID 41404293, 2025).
PHLPP1 also shares sentences with these, for which no sentence is quoted: metabolic disease (4 papers); Anxiety (3); leukemia (3); gallbladder carcinoma (2); glioma (2); liver cancer (2); lymph node metastasis (2); lymphoma (2); periodontal disease (2); Alzheimer disease (1); brain injury (1); calculus (1); cardiovascular disease (1); cervical cancer (1); colon (1); depression (1); diabetic nephropathy (1); endometrial adenocarcinomas (1); endotoxemia (1); gastric tumor (1); Glucose intolerance (1); injury (1); Intellectual disability (1); intervertebral disc degeneration (1); leprosy (1); multiple myeloma (1); neurological disorders (1); oral diseases (1); Paget’s disease of (1); pancreatic ductal adenocarcinoma (1).
A further 4 diseases each share a sentence with PHLPP1 in 1 paper.